HDAC6 (histone deacetylase 6)
Diseases named in the same sentence as HDAC6 in open-access papers (continued):
Sharing a sentence is not in itself a finding about the gene and the disease.
Hypertension (13 papers, 2019 to 2025). The presence of chronic increased pressure in the systemic arterial system. "Histone deacetylase 6 (HDAC6) is implicated in the pathophysiology of hypertension‐related vascular diseases." (PMID 32755037, 2020). "Finally, increased myofibril stiffness in HDAC6-deficient mice was associated with exacerbated DD in response to hypertension or aging." (PMID 35575093, 2022). "HDAC6 expression is increased in ANG II‐induced hypertension, which leads to the deacetylation and ubiquitination‐mediated degradation of CSEγ, and participates in the occurrence of hypertension." (PMID 40497340, 2025). "Recent studies have focused on the crucial role of HDAC6 in regulating cardiovascular diseases such as atherosclerosis, myocardial infarction, myocardial hypertrophy, myocardial fibrosis, hypertension, pulmonary hypertension, and arrhythmia." (PMID 38947757, 2024). "A study to investigate the role of HDAC6 in hypertension found that Ang II upregulated HDAC6 mRNA and protein expression." (PMID 35752619, 2022). "Conversely, the zinc‐dependent deacetylase HDAC6 plays a pathologic role in heart and vessel dysfunctions such as hypertension, atherosclerosis, cardiac hypertrophy and fibrosis." (PMID 32755037, 2020). "HDAC6 plays a significant role in the cardiac dysfunction mediated by angiotensin II (AngII), an inducer of hypertension." (PMID 32755037, 2020). "In summary, HDAC5 plays an important role in the early pathogenesis and vascular remodelling of ANG II‐induced hypertension, HDAC6 affects vascular relaxation function, while HDAC1 and HDAC2 regulate the transcription of genes related to blood pressure regulators." (PMID 40497340, 2025). "Tubastatin A (TubA), a selective HDAC6 inhibitor, could prevent hypertension progression, and ascorbic acid has shown efficacy in preventing hypertension occurrence and development." (PMID 39125279, 2024). "Hdac6 deficient mice develop greater diastolic dysfunction in response to hypertension and aging, suggesting that HDAC6-mediated control of titin phosphorylation could be important for normal cardiac function and in response to stress and normal aging." (PMID 38660537, 2024). "Lemon and colleagues investigated whether HDAC6 could become a mediator of hypertension‐induced cardiac remodelling by applying selective HDAC inhibitors in multiple rodent models of hypertension." (PMID 39232846, 2024). "LMK235, class I and HDAC6-preferential HDAC inhibitor, ameliorated hypertension via inhibition of vascular contraction and vessel hypertrophy in mouse Ang II-infusion model and spontaneously hypertensive rat model." (PMID 31655853, 2020). "Here, we report that LMK235, a class I and histone deacetylase (HDAC6)‐preferential HDAC inhibitor, reduces hypertension via inhibition of vascular contraction and vessel hypertrophy." (PMID 30734467, 2019). "In summary, the present study showed that LMK235 is a class I and HDAC6‐preferential HDAC inhibitor and attenuates hypertension through relaxation of vasoconstriction or suppression of aortic wall thickness." (PMID 30734467, 2019). "Although cardiac HDAC6 activity was shown to be increased in chronic hypertension, the HDAC6-selective inhibitor tubastatin A did not reduce hypertension in Ang II-infused mice." (PMID 30830950, 2019). "We demonstrated that the HDAC6-selective inhibitor, tubastatin A, did not affect high blood pressure in an angiotensin II-induced hypertensive mouse model." (PMID 31223486, 2019). "We also recently reported that tubastatin A, an HDAC6‐specific inhibitor, could increase CSE acetylation and enhance its protein levels and H2S production, thereby helping to attenuate the vasoconstriction and hypertension induced by AngII." (PMID 32755037, 2020). "However, the HDAC6-selective inhibitor, tubastatin A, did not attenuate angiotensin II-induced hypertension." (PMID 31223486, 2019).
liver cancer (13 papers, 2015 to 2025). An epithelial or non-epithelial malignant neoplasm that arises from the liver. "HDAC6 is significantly down-regulated in liver cancer tissues, and low expression of HDAC6 is closely associated with poor prognosis." (PMID 33109235, 2020). "HDAC6 was downregulated in hypoxia and thus led to an increase in lamin A crotonylation and liver cancer proliferation." (PMID 35977926, 2022). "This is disrupted in hypoxia, where HDAC6 is downregulated and leads to lamin A crotonylation and promotion of liver cancer proliferation." (PMID 35977926, 2022). "To further investigate the role of HDAC6 in HCC, we evaluated the expression levels in the normal liver cell line LO2 and liver cancer cell lines Huh-7, Hep3B, Bel-7402, and HepG2 and demonstrated that HDAC6 was indeed highly expressed in HCC cells." (PMID 35676659, 2022). "We demonstrated that a specific HDAC6 inhibitor, Nexturastat A, increased the crotonylation of liver cancer cells after NaCr treatment." (PMID 35977926, 2022). "Together, these data suggested that the HDAC6/ lamin A complex modulated the senescence of liver cancer cells." (PMID 35977926, 2022). "However, there are opposing data on the effect of HDAC6 on Beclin-1 expression obtained on liver cancer cells, showing that HDAC6 overexpression activated c-Jun NH2-terminal kinase (JNK) and increased the phosphorylation of c-Jun, which induced Beclin-1-dependent autophagy." (PMID 38258065, 2023). "We found that NEO1 was positively regulated by HDAC1, 2, and YY1, whereas was negatively regulated by HDAC6 in LIHC, suggesting that NEO1 may play an important role in the proliferation and apoptosis of liver cancer cells." (PMID 41407823, 2025). "It was reported that the overexpression of HDAC6 could activate JNK and increase the phosphorylation of JNK in liver cancer cells." (PMID 31639165, 2019).
Sepsis (13 papers, 2016 to 2024). Sepsis is defined as life-threatening organ dysfunction caused by a dysregulated host response to infection. "Mechanistically, HDAC6, mainly located in the cytosol, has been shown to associate during sepsis with HDAC11 in the nucleus in antigen-presenting cells, inducing IL-10 expression." (PMID 30654448, 2019). "HDAC6 inhibition significantly attenuated the sepsis-associated pulmonary, hepatic, and renal injury, suggesting that inhibition of HDAC6 may form the basis of a potential therapy for sepsis and related disorders." (PMID 32221047, 2020). "Inhibition of HDAC6 significantly attenuated CLP-induced sepsis through inhibition of mitochondrial dysfunction and reduced oxidant production, thus protecting the rats from oxidative injury." (PMID 32221047, 2020). "To investigate in further detail how HDAC6 promotes oxidative stress during CLP-induced sepsis, we used lentivirus-mediated gene expression and suppression methods to generate HDAC6-overexpressing cells and HDAC6 knockdown U937 cells." (PMID 32221047, 2020). "HDAC6 mRNA expression was higher in PBMCs from patients with sepsis than that in healthy control PBMCs (1.5 ± 0.25 vs 0.4 ± 0.1, P < 0.001)." (PMID 32221047, 2020). "In the present study, we found that the expression of HDAC6 was significantly higher in PBMCs from sepsis patients than in PBMCs from healthy control participants." (PMID 32221047, 2020). "We also noticed that the expression of HDAC6 was dramatically higher in PBMCs derived from sepsis patients than that in PBMCs from healthy control participants." (PMID 32221047, 2020). "To further understand the effects of HDAC6 during sepsis development, we created a rat model of CLP-induced sepsis." (PMID 32221047, 2020). "We also observed that HDAC6 expression was higher while PHB1 expression was lower in the rats with CLP-induced sepsis compared to that in rats in the control group; this was consistent with the data obtained from human sepsis patients." (PMID 32221047, 2020). "In response to the polymicrobial sepsis model initiated by cecal ligation and puncture (CLP), it was shown to be associated with HDAC6 activation." (PMID 30654448, 2019). "Inhibition of HDAC6 protects against ischaemic stroke and prolongs survival after sepsis in animal models." (PMID 30134806, 2018). "Another similar study showed that specific knockdown of HDAC6 inhibited the LPS-induced TLR4-MAPK/NF-κB signaling pathway in macrophages and promoted activation of the Nrf2-HO-1 anti-inflammatory signaling pathway and improved sepsis-associated ALI." (PMID 37175583, 2023). "Interestingly, also HDAC6 is involved in sepsis and its inhibition improves survival in murine sepsis models." (PMID 35592335, 2022). "Studies using mouse CLP models of sepsis have shown that drugs, such as Tubastatin A, which is a selective inhibitor of histone deacetylase 6, restore B cell counts during sepsis and have an added effect of increasing the number of innate immune cells, such as macrophages and neutrophils." (PMID 34356636, 2021). "To determine whether selective inhibition of HDAC6 could attenuate CLP-induced sepsis in vivo, we used Tri A (selective HDAC6 inhibitor) to treat the rats with CLP-induced sepsis, and then evaluated possible signs of tissue pathology." (PMID 32221047, 2020). "Taken together, these results indicated that HDAC6 may promote the development of sepsis via regulation of PHB1-mediated mitochondrial function and homeostasis, in vivo." (PMID 32221047, 2020). "To investigate the potential mechanism by which HDAC6 may promote sepsis development, we first determined the mitochondrial respiratory control rate, and then tested whether it correlated with the expression of HDAC6 and/or PHB1." (PMID 32221047, 2020). "Third, broad-spectrum antibiotic administration is considered to be the standard of care for patients with sepsis, but whether this treatment affects the expression of HDAC6 and PHB1 needs to be studied." (PMID 32221047, 2020).
Sepsis (continued). "This may explain the mixed results of HDACis in sepsis as earlier trials used the less selective compounds inhibiting both classes I and II HDACs whereas the HDAC6 inhibitors had more positive results." (PMID 27519803, 2016). "In a CLP mouse model, the HDAC6 inhibitor, Tubastatin A, was shown to restore B lymphocyte percentage, as well as other innate immune cells, to improve sepsis prognosis, which suggests the potential role of histone deacetylation to B cell down-regulation in sepsis." (PMID 36774341, 2023). "It has been shown that HDAC6 can activate STAT1 by promoting phosphorylation at Y701 of STAT1, which further increases interferon-regulatory factor-1 (IRF-1) expression, leading to increased iNOS levels in LPS-activated macrophages, thus promoting sepsis-associated ALI." (PMID 37175583, 2023). "In addition, HDAC6 overexpression in macrophages dose-dependently induced MAPK activation and also promoted activation of NF-κB and AP-1 signaling pathways, contributing to sepsis-associated ALI." (PMID 37175583, 2023). "Since we found that HDAC6 inhibition seems effective in dampening the inflammatory response in vitro and plays a role in sepsis in vivo, we next focused on ITF3756 and asked whether the inhibitor could impinge on the TNF-α induced pro-inflammatory program in monocytes." (PMID 35592335, 2022). "Taken together, these data implied that HDAC6 may serve as a target in the treatment of sepsis." (PMID 32221047, 2020). "HDAC6 inhibits the mitochondrial protein PHB1, leading to increased oxidants and oxidative stress in sepsis." (PMID 35954428, 2022). "The expression of HDAC6 at mRNA and protein levels was significantly higher in rats with CLP-induced sepsis compared with that in control rats (2.77 ± 0.22 vs 0.71 ± 0.14, P < 0.001)." (PMID 32221047, 2020). "Taken together, these results indicated that HDAC6 expression has a significant inverse correlation with PHB1 levels, and that it directly correlates with disease severity in patients with sepsis." (PMID 32221047, 2020). "We also analyzed the correlations among HDAC6, PHB1, and mitochondrial dysfunction, and investigated their role in the development and progression of sepsis." (PMID 32221047, 2020). "To investigate the effects of HDAC6 and PHB1 on the development of sepsis, we measured the expression of HDAC6 and PHB1 in peripheral blood mononuclear cells (PBMCs) derived from sepsis patients and healthy controls." (PMID 32221047, 2020). "Consistently, increased HDAC6 expression was observed in the cytoplasm of renal tubular cells, which commonly results in rhabdomyolysis-induced AKI, in a sepsis animal model." (PMID 30134806, 2018). "In the present study, we examined the effects of HDAC6 and PHB1 on the progression of sepsis." (PMID 32221047, 2020). "To evaluate whether HDAC6 could serve as a therapeutic target in sepsis, we treated rats with CLP-induced sepsis with a selective HDAC6 inhibitor (Tri A)." (PMID 32221047, 2020). "A negative linear correlation was observed between HDAC6 expression and that of PHB1 in PBMCs from sepsis patients (r2 = 0.6271, P = 0.0003)." (PMID 32221047, 2020). "Of note, when we analyzed the correlation between HDAC6 and PHB1 in PBMCs from sepsis patients, we found a negative linear correlation between the expression of HDAC6 and PHB1, meaning that the expression of PHB1 may be downregulated by HDAC6 during the development of sepsis." (PMID 32221047, 2020).
tauopathy (13 papers, 2014 to 2026). Neurodegenerative disorders involving deposition of abnormal tau protein isoforms (tau proteins) in neurons and glial cells in the brain. "HDAC6 is also reported to regulate tau proteins found in tauopathy-associated neurodegenerative diseases." (PMID 34944907, 2021). "Overall, the behavioral analysis suggests that PHK mice do not show acquisition of spatial learning, indicating that loss of HDAC6 exacerbates hippocampal-dependent cognitive decline in a mouse tauopathy model." (PMID 33139698, 2020). "For instance, targeting HDAC2 with the specific inhibitor mithramycin improved neuronal plasticity in cellular model of AD, while HDAC6 inhibition improved cognitive decline associated with HD, AD, tauopathy, and Charcot-Marie-Tooth disease." (PMID 33315879, 2020). "Furthermore, our data potentially reconcile a long-standing controversy as to whether loss of HDAC6 is beneficial or detrimental, as HDAC6 loss exacerbated disease progression in a tauopathy model but restored cognition in a model of Aβ plaque deposition." (PMID 33139698, 2020). "HDAC6 inhibition or knockdown (KD) have also been investigated in mouse models of tauopathy, with conflicting observations." (PMID 41330635, 2026). "Pharmaceutical inhibition of HDAC6 is a potential therapeutic strategy for tauopathy, and T-518 is a particularly promising drug candidate." (PMID 34326423, 2021). "Using mass spectrometry, we identify a novel HDAC6-regulated tau acetylation site as a disease specific marker for 3R/4R and 3R tauopathies, supporting uniquely modified tau species in different neurodegenerative disorders." (PMID 33139698, 2020). "Future efforts are needed to more clearly determine the impact of HDAC6 inhibition on tau pathology, particularly at early versus late stages of tauopathy progression." (PMID 33139698, 2020). "Selective HDAC6 inhibition has shown varying degrees of neuroprotection in some tauopathy or amyloid-beta (Aβ) plaque models." (PMID 33139698, 2020). "Mounting evidence supports the notion that administration of HDAC6 inhibitors and MT-stabilizing drugs improve transport defects and cognition in transgenic mouse models of tauopathy." (PMID 28819043, 2017). "As the rationale for targeting HDAC6 for the treatment of tauopathies is based on elevating tau acetylation on KXGS motifs, it should be mentioned that recent reports have suggested a pathogenic role for tau acetylation in disease." (PMID 23962722, 2014). "Modification of tau pathology by specific inhibition of HDAC6 presents a potential therapeutic approach in tauopathy." (PMID 24576665, 2014). "We review here the rationale supporting the utilization of HDAC6 inhibition to enhance tau acetylation as a novel therapeutic strategy for tauopathies." (PMID 25031639, 2014). "Based on recent evidence that HDAC6 regulates tau acetylation on KXGS motifs, it is of particular interest that, in a Drosophila model of tauopathy, loss of HDAC6 activity rescued tau-induced microtubule defects in both neuronal and muscle cells." (PMID 25031639, 2014). "Here, we report that the novel HDAC6 inhibitor T-518 harboring oxadiazole instead of hydroxamate as the ZBG acts as a potent, selective, orally bioavailable, and brain-penetrant HDAC6 inhibitor, and that T-518 has therapeutic effects in a mouse model of tauopathy." (PMID 34326423, 2021). "Here the authors show that HDAC6 protects against tau accumulation in a mouse model of tauopathy." (PMID 33139698, 2020). "We propose that a HDAC6-dependent surveillance mechanism suppresses toxic tau accumulation, which may protect against the progression of AD and related tauopathies." (PMID 33139698, 2020). "In contrast to alleviating tauopathy progression, our results to this point suggest that HDAC6 depletion might enhance pathological tau and accelerate tauopathy in vivo." (PMID 33139698, 2020).